CD4 (CD4 molecule)
Diseases named in the same sentence as CD4 in open-access papers (continued):
Sharing a sentence is not in itself a finding about the gene and the disease.
tumor (continued). "For example, despite the known anti-tumor effect of CD8+ cytotoxic cells, a low CD4:CD8 ratio has been associated with worse 5-year survival rate in cervical SCC, likely due to the inactivated or underprimed status of CD8+ cells." (PMID 40270290, 2025). "In contrast, tumor-promoting immune cells such as M2-macrophages, Treg, CD4+T, etc. produce metabolic reprogramming that favors their proliferation and function." (PMID 40356913, 2025). "Lipocalin‐2 (LCN2), overexpressed in CRC, disrupts CD4+ T‐cell iron homeostasis by accelerating iron efflux, triggering apoptosis and fostering a tumour‐permissive niche." (PMID 40785042, 2025). "The experimental results indicate that the heightened methylation status of immune-related genes in COPD-associated cancers corresponds with a lower infiltration of CD3+ and CD4+ immune cells in the surrounding tumor stroma." (PMID 40332320, 2025). "In the immunogenic early stages of lung cancer, the tumor mass is infiltrated by mDCs, CD4+, and CD8+ T cells, whereas in later stages, it is dominated by MDSCs, TAMs, Tregs, and CAFs." (PMID 40136652, 2025). "More importantly, Spp1-cKO mice exhibited significantly reduced tumor growth and better ICI treatment efficacy based on tumor volume, paralleled by an increase in tumor-infiltrating CD4+/CD8+ T cells and DNT cells." (PMID 40312419, 2025). "In PDAC, CD3+ markers (90%) are indicative of tumor-infiltrating lymphocytes (TILs), predominantly of the CD4+ subtype." (PMID 41155765, 2025). "As a result of environmental changes, CD4 T cells are able to eliminate tumor cells in various ways and exhibit a high degree of plasticity and differentiation potential." (PMID 40874228, 2025). "As the disease advances, there is a notable decline in the proportions of naïve and memory CD4+ T cells within non-tumor areas, accompanied by a progressive accumulation of exhausted CD4+ and CD8+ T cells." (PMID 41476608, 2025). "Flow cytometry analysis demonstrated that C9orf50 interference significantly increased tumor infiltration of both CD4+ and CD8+ T cells, with significant expansion of the Th1 and IFN‐γ‐producing CD8+ T cell subset." (PMID 41472851, 2025). "In contrast to CD8+, CD4+ T-cell infiltration shows mixed prognostic associations, as subsets like Tregs (CD4+FoxP3+) actively suppress CD8+ effector function through TGF-β, IL-10, and adenosine-mediated pathways, blunting anti-tumor immunity." (PMID 41007774, 2025). "Flow cytometry analysis showed a significantly higher level of cytotoxic CD8+ T cells (p < 0.001) and helper CD4+ T cells (p < 0.05) infiltration in the B16‐OVA model at both tumour stages (250 and 1000 mm3) compared to other models." (PMID 40898695, 2025). "To investigate the role of CD4+ T cells in TSLP-mediated tumor protection, we transferred naïve CD4+ T cells from WT mice into Rag1–/– (Rag1KO) mice with or without TSLP overexpression." (PMID 39744942, 2025). "Linoleic acid (LA) uptake triggers mitochondrial oxidation and ROS generation in T cells, leading to cell death, to which CD4+ T cells are particularly sensitive, and promotes tumor cell growth." (PMID 40356913, 2025). "Among them, activated memory CD4+ T Cells, regulatory T cells (Tregs), T follicular helper cells, M0 macrophages, as well as M1 macrophages were more infiltrated in tumor samples, while M2 macrophages were more infiltrated in normal samples." (PMID 40496561, 2025). "We have isolated CD4+ T cells from the tumor-infiltrating immune cells and tumor-draining lymph nodes of tumor-bearing mice." (PMID 40563574, 2025). "In our analysis of ASCC3 immune infiltration and single-cell sequencing, we found that ASCC3 is associated with immune-activating cells, such as resting CD4+ memory T cells and conventional CD4+ T cells, in the tumor immune microenvironment." (PMID 40881169, 2025).
tumor (continued). "Our present findings demonstrate that calcipotriol-induced TSLP also leads to the activation of CD4+ Th2 cells that promote tumor suppression during late-stage tumor progression." (PMID 39782693, 2025). "For instance, the immunosuppressive cells MDSC which stimulates the growth of tumour by the suppression of CD4+ and CD8+ T cells, which are essential immune cells that have antitumour properties." (PMID 40407951, 2025). "We propose that tumor cells reshape circulating immune profiles by promoting inflammatory monocytes while depleting critical immune subsets such as B cells, CD8 T and CD4 T cells, fostering a pro-tumor environment." (PMID 40340807, 2025). "In vivo, AEVs inhibited tumor growth by shifting macrophage polarization from the M2-like to the M1-like phenotype, and synergistically enhancing the recruitment of CD8+ and CD4+ T cells into the tumor microenvironment." (PMID 41029711, 2025). "On the other hand, there are subpopulations of T cells, such as CD3+/CD4+ regulatory T cells, that are known to promote tumor progression." (PMID 40231254, 2025). "Although it had a small sample size, our m-fIHC analysis confirmed the significant increase in CD4+ T-lymphocytes (CD3+/CD8−) in the tumor area of TIL-B-rich tumors, while CD8+ T-lymphocyte and CD163+ macrophage infiltration levels were comparable." (PMID 39796740, 2025). "Some investigators have demonstrated that IL-2 production by CD8+ T cells indirectly upregulates anti-apoptotic molecules on the surface of conventional CD4+Foxp3+ Tregs in the tumor microenvironment to promote tumor growth." (PMID 40553564, 2025). "Elevated tumor-infiltrating CD4+ T cell levels correlated with reduced OS and progression-free survival in KIRC patients." (PMID 40909125, 2025). "We observed that tumours with PR had a significantly higher proportion of CD4+ T cells and CD8+ T cells compared to PD and SD tumours." (PMID 40985995, 2025). "TIMER2 immune association analysis showed a significant negative correlation between VWF and tumor purity (proportion of tumor cells in the tumor microenvironment) (r = −0.159, p = 3.09 × 10−3) and CD4 + T cells (r = −0.134, p = 1.28 × 10−2)." (PMID 40699668, 2025). "In such cases, NSCLC exhibits a non-T cell inflammatory microenvironment with limited infiltration of CD3+, CD4+, and CD8+ T cells, along with low expression of PD-L1 in tumour cells, despite having a moderate to high tumour mutation burden (TMB)." (PMID 40429821, 2025). "Our research found that the expression of CXCR2P1 was positively correlated with the number of M1 macrophages and activated CD4+ T cells in the tumor microenvironment." (PMID 40176817, 2025). "The anti‐tumor response was reflected in the increased invasion of CD4+, CD8+ T cells, myeloid CD11b+ cells, and NK cells in tumor tissue at 7 days post‐therapy." (PMID 40051045, 2025). "Females with CRC exhibited higher CD4+ T cell infiltration in tumor tissue (22.04% vs. 10.26%), metastatic lymph nodes (39.54% vs. 8.56%), and uninvolved colon (3.91% vs. 2.72%)." (PMID 40807160, 2025). "In line with this, CD4+ T cells most commonly recognize cancer antigens in the tumour microenvironment through indirect display on professional APCs, consistent with the fact that many cancers do not express MHC‐II." (PMID 41416931, 2025). "CD8+ T cells play a significant role in tumor antigen presentation, while CD4+ T cells are also essential for supporting the proper function of CD8+ T cells." (PMID 39743555, 2025). "CD4 + Th cells modulate the tumor microenvironment by secreting cytokines such as IFN-γ, TGF-β, IL-4, IL-5, and IL-6." (PMID 40441260, 2025). "Key components of anti-cancer immunity include various immune cells such as cytotoxic T cells (CD8+), which target and kill tumor cells, and helper T cells (CD4+), which assist in activating and regulating immune responses." (PMID 40006729, 2025).
tumor (continued). "Treg cells, a subset of CD4+ T cells with immunosuppressive functions, can inhibit anti-tumor immunity and promote tumor growth by suppressing the activity of cytotoxic T cells and other immune cells." (PMID 40281780, 2025). "Risk scores positively correlated with M0 macrophages and negatively with resting CD4 memory T cells, consistent with a tumor-promoting immune landscape influenced by hypoxia and MYOSLID-driven pathways." (PMID 40149492, 2025). "Increased CD154 expression and cytokine release can effectively activate CD4+ tumor-infiltrating lymphocytes (TILs) during anti-PD-1 therapy, which promotes dendritic cell development and enhances CD8+ TIL multiplication." (PMID 39991589, 2025). "After calculating the individualized CD8+ to CD4+ T-cell ratio as a suitable surrogate of tumor immune activation, the results show that this ratio was significantly elevated in tumors treated with Ad5/11-αCD3TAT-Trimer." (PMID 39789356, 2025). "To evaluate the effects of targeting ephrinB2 on lymphocyte extravasation into the TME, we conducted specialized flow cytometry experiments involving adoptive transfers of CD4 + T cells into tumor-bearing mice." (PMID 39489818, 2025). "Conversely, the high PS group exhibited higher infiltration of activated memory CD8+ and CD4+ T cells, indicating a more robust anti-tumor immune response, consistent with the findings." (PMID 41368643, 2025). "The anti-tumor effect was further enhanced when IL-2 was used to stimulate CD4+ T cells during EV production, resulting in an increased yield of CD4+ T cell-derived EVs and further strengthening the CD8+ T cell immunity." (PMID 40006624, 2025). "When assessing tumor infiltration in engineered DC-treated mice, we observe a significant increase in the numbers of CD4+ and CD8+ T cells in the tumors as compared to control treatments." (PMID 40733726, 2025). "We observed that M002-treated CD4+ T cells were more capable of killing GSC005 tumor cells than CD4+ T cells from the saline control at all effector-to-target (E/T) ratios at both 14 and 35 days post-treatment." (PMID 39885128, 2025). "Our preclinical studies highlight an opportunity to exploit the senescence program and CD4 T cell–mediated mechanisms to achieve long-term tumor-immune equilibrium and control with RAS-targeted therapies." (PMID 40299790, 2025). "Tumor-infiltrating CD4+ T28zT2 T cells exhibited phenotypes of memory-like T cells with high CXCR3 expression." (PMID 40107245, 2025). "To further investigate CTSS-mediated tumor immunity, we assessed CD4+ T-cell and M2 macrophage (CD163+ cells) infiltration in MC38 tumors." (PMID 40794185, 2025). "A higher presence of inactive mast cells and CD4 T-helper cells is associated with better overall survival outcomes.This suggests that the undifferentiated macrophages present in the tumor microenvironment may undergo polarization into pro-tumor M2 macrophages." (PMID 40510341, 2025). "The assessment encompassed a range of immune cells including B cells, CD8+ T cells, CD4+ T cells, macrophages, neutrophils, and dendritic cells to obtain a comprehensive understanding of the impact of each gene on the tumor microenvironment." (PMID 40290432, 2025). "VEGFR2 is selectively expressed on human FOXP3 high Tregs among CD4+ T-cells in tumor and VEGFA induces the recruitment and proliferation of Tregs via activation of VEGFR2 signaling." (PMID 39985645, 2025). "We also discovered that LAG3 + T cells stayed away from tumor cells after treatment, particularly LAG3 + CD4 + T cells, whose changes of minimum distance to tumor cells were statistically significant (31.01 μm vs 42.98 μm, p = 0.023)." (PMID 40411616, 2025). "AXL/MER RTK signaling between CD4+ T cells and microglia enhances tumor suppression through IFNγ-dependent activation and phagocytosis." (PMID 40332008, 2025).
tumor (continued). "In another murine SCC model, VEGF-D influenced the immune microenvironment by reducing Th2 inflammation, increasing CD8+ T cells, and decreasing CD4+ T cells, macrophages, and mast cells, leading to tumor regression in early stages." (PMID 40868818, 2025). "Another mechanism is the formation of HPV antigen-specific regulatory T (Treg) cells, whose purpose is to suppress both CD8+ and CD4+ cells in the tumor microenvironment." (PMID 41007768, 2025). "To identify the immune-related genes that play a regulatory role in the regulation of macrophages, monocytes, NK cells and CD4 + T cells, we used the online platform of the Tracking Tumor Immunophenotype." (PMID 40464853, 2025). "CD8+ T lymphocytes act as primary cytotoxic effectors capable of directly eliminating tumor cells, while CD4+ T helper lymphocytes facilitate the activation of cytotoxic T lymphocytes (CTLs)." (PMID 41444555, 2025). "Owing to these important roles of Th1 in tumor immunity, CD4+ T cells are used alongside CD8+ T cells in CAR T‐cell therapy." (PMID 40257446, 2025). "The majority of these tumor-infiltrating CD4+ T cells were activated (CD69+); however, the activation was not influenced by 2015." (PMID 39820127, 2025). "Intriguingly, various studies have reported that TEVs interact with or are taken up by CD4 + T cells, thereby altering anti-tumor immunity." (PMID 40908470, 2025). "Afterwards, they exhibited a transition towards exhausted T‐cell phenotypes in the Post stage, coinciding with a progressive decline in the activity of both Cd8+ and Cd4+ T tumour cells." (PMID 40887856, 2025). "The effective advantage of combining therapy with TTFields and anti-PD-1 is that it promotes the infiltration of a large number of CD8+ T and CD4+ T cells into the tumor tissue, thereby improving the tumor microenvironment." (PMID 40098106, 2025). "Following CD4+ T cell priming, they can in turn licence cDCs, which enables anti‐tumour CD8+ T cell responses." (PMID 40878038, 2025). "It has been proposed that peripheral CD4+ T cell differentiation patterns can independently predict tumor progression in NSCLC." (PMID 40346687, 2025). "More recently, the role of tumor-infiltrating CD4+ T cells in the anti-tumor immune response, particularly in the context of immunotherapies such as immune checkpoint blockade (ICB) and adoptive cell transfer (ACT), has garnered increased interest." (PMID 40775564, 2025). "CD4+ Tem (CD4+ effector memory T cells) can recognize and bind to antigens on the surface of tumor cells to trigger an immune response." (PMID 40438115, 2025). "Although the details of this effect are still being investigated, with new insights being uncovered, there is general agreement about this beneficial effect (against tumor growth) of CD4+ → CD8+ T cell interaction." (PMID 41002395, 2025). "This is initiated by CD4+ effector T cells and activated iNOS-expressing tumor-killer monocytes and macrophages." (PMID 40422244, 2025). "These regions are distinct from those surrounding proliferative tumor lesions that have abundant CD4+ and CD8+ T cells, alveolar macrophages, and DCs." (PMID 40568095, 2025). "MLKL-mRNA treatment rapidly induces T cell responses directed against tumor neoantigens, and requires both CD4+ and CD8+ T cells to prevent tumor growth." (PMID 41303584, 2025). "IVM has been used to study the dynamics of adoptively transferred CD4+ T cells, shedding light on their actual anti‐tumor functions using fluorescently labeled CD4+ T cells collected from mice." (PMID 40257446, 2025). "In certain contexts, CD4 T cells can also exert direct cytotoxic effects on tumor cells expressing MHC class II molecules or facilitate anti-tumor immunity through the secretion of cytokines such as IFN-γ." (PMID 40076932, 2025). "CD8 T cells showed TdTomato expression only in tumor, while NK cells and CD4 T cells displayed intermediate levels of fluorescence, in both bone marrow and tumor." (PMID 41331250, 2025).
tumor (continued). "In contrast, CD4+ regulatory T (Treg) cells promote tumor progression by suppressing tumor-specific immunity, including CD8+ T-cell activity." (PMID 41008548, 2025). "In blood, before PD-1 blockade, tumor-TCR-matched CD4+ cells were predominantly GZMB+ in pre-atezolizumab blood (average 35%–37% of branches A and B), with a minority of GZMK+ (2.8%–5.2% of branches A and B)." (PMID 40299576, 2025). "We found that the proportion of tumor‐infiltrating CD4+CD25+Foxp3+ Tregs, especially the CCR6+ Treg subpopulation, was attenuated." (PMID 39853961, 2025). "Conventional DCs (which are CD103+) present antigen via MHCI and MHCII to CD8+ and CD4+ T-cells, to induce a tumor cytolytic response or a Th1/Th2/Th17 response respectively." (PMID 40236693, 2025). "While CD8+ cytotoxic T lymphocytes contribute to tumor destruction, CD4+ T lymphocytes can support tumor progression through immune modulation." (PMID 40284848, 2025). "CD4+ T-cells play a pivotal role in cancer immunology, functioning as both tumor-suppressing and tumor-promoting agents depending on their differentiation and cytokine profiles." (PMID 40860882, 2025). "Taken together, these results suggest that a proper expression of Bcl-6 relative to T-bet in CD4+ T cells at early and late stages of anti-tumor responses was required for the sustained survival outcome of M002 treatment." (PMID 39885128, 2025). "To further investigate the role of direct TSLP signaling to CD4+ T cells in the establishment of TSLP-mediated tumor protection in the skin, we utilized CD4+ T cell transfer to TslptgTslpr–/– (TslprKO) animals." (PMID 39744942, 2025). "A study demonstrated that CIITA serves as a master regulator of MHC class II expression and is critical for the induction of tumor immunogenicity through enhanced CD4+ T cell activation." (PMID 40861816, 2025). "These factors may recruit and modulate CD4+ T cells, which also had higher levels in PM tissue, into Th2, Th17, or Tregs with tumor‐promoting responses, and may also increase the expression of immune checkpoint molecules on T cells/tumor cells, causing T cell exhaustion." (PMID 39739693, 2025). "These nanoparticles improve intracellular drug delivery, synergistically inhibit tumor growth, and enhance survival in lung cancer models by modulating immune responses, increasing CD4+ and CD8+ T cells, reducing Treg cells, and activating cytokine production." (PMID 39742149, 2025). "Our study demonstrated that VVL-GL7 led to a substantial augmentation in the number of memory T-cells within tumor tissues, particularly on day 14, and the proportion of CD4+ and CD8+ TCM and TEM cells was significantly higher than that of controls." (PMID 40299475, 2025). "The levels of CD3+INFγ+, CD8+INFγ+, and CD4+INFγ+ T cells in peripheral tissues were quantified as tumor-specific T cells following co-incubation with the antigen-loaded nanoparticles." (PMID 41019037, 2025). "γδ T cells enable tumor cell killing, inducing CD4+ and CD8+ T cell differentiation and proliferation." (PMID 40741411, 2025). "This combination therapy reversed the early depletion of CD4+ T-cells, enhanced the inhibitory effect of PD-1 checkpoints on tumor cells, and improved the overall immunotherapeutic response." (PMID 40177243, 2025). "It has been confirmed that CD4+ T cells can directly kill tumor cells via the cytolytic mechanism, and they can also indirectly exert their effect by modulating the TME." (PMID 40534850, 2025). "Consistent with the crosstalk between APCs and tumor-infiltrating CD4+ T and B cells,59,60Cd40lg exhibited high expression in these two TME components." (PMID 40312419, 2025). "IL-16 administration improved anti-tumor immune responses by enhancing Th1 cell polarization through the inhibition of glutaminase catabolism via the down-regulation of glutaminase in CD4 + cells." (PMID 40598593, 2025).